CD44 (CD44 molecule (IN blood group))
Diseases named in the same sentence as CD44 in open-access papers (continued):
Sharing a sentence is not in itself a finding about the gene and the disease.
acute myeloid leukemia (continued). "In acute myeloid leukemia (AML) CD44 is required for the transport to the stem cell-supportive osteogenic niche and anti-CD44 alters the fate of AML-IC by inducing differentiation." (PMID 24684724, 2014). "In acute myeloid leukemia (AML), our results point to a decisive role for CD44 in induction of stemness and resistance to chemotherapy." (PMID 38761292, 2024). "For instance, the type I transmembrane protein CD44, which was upregulated in venetoclax-resistant MOLT-16 and ALL-SIL cells, was involved in the regulation of venetoclax sensitivity in acute myeloid leukemia." (PMID 36902436, 2023). "Previously, we reported that sustained degradation of BRD4 led to downregulation of CD44, MYC, and CXCR4 in acute myeloid leukemia (AML) stem cells and improved survival in a mouse model of AML." (PMID 35173274, 2022). "Similar observation was previously reported in acute myeloid leukemia (AML), where CD44-triggered activation of PI3K/Akt signaling pathway downregulates p27 and cytoplasmic relocation." (PMID 33911148, 2021). "CD44-targeting antibodies showed a significant anti-tumor effect in xenograft pancreatic and squamous cell carcinoma models, as well as in acute myeloid leukemia (AML)." (PMID 33335857, 2020). "A study with human acute myeloid leukemia (AML) cell showed that an activated anti-CD44 antibody (H90) reduced the leukemic repopulation by alteration of the behavior of AML leucocyte stem cells (LSC) by annulling AML LSC homing, resulting in tumor-initiating cell death." (PMID 27200096, 2016). "Two clinical trials are underway to examine the pharmacokinetics, pharmacodynamics, safety, and efficacy of RG7356 in acute myelogenous leukemia (AML) patients and patients with metastatic and/or locally advanced CD44-expressing solid tumors." (PMID 25941526, 2015). "This concept was first established in acute myeloid leukemia (AML) and subsequently also in a number of solid tumors such as breast cancer where a CD44+/CD24−/low CSC population was identified, in brain tumors, colon cancer, and melanomas." (PMID 21602936, 2011). "Depletion of Flot2 demonstrated its essential role in CD44 expression, but its absence affects the cytoskeleton, polarity, and homing defects, as well as the progression of chronic myeloid leukemia (CML), while acute myeloid leukemia (AML) remains unaffected." (PMID 37795089, 2023). "Whether CD44-targeted therapy is an effective strategy for the treatment of ALL with MLL-r and acute myeloid leukemia requires further investigation." (PMID 32347296, 2020). "In this context, a previous study showed that activated anti-CD44 antibody (H90), when used in human acute myeloid leukemia (AML) cells, reduced the leukemic repopulation by altering the fate of AML leukocyte stem cells (AML LSC), and by abrogating AML LSC homing, leading to their death." (PMID 25999946, 2015). "CD44 is expressed in several malignant hematopoietic disorders, including both T-ALL and acute myeloid leukemia (AML)." (PMID 30430079, 2018).
oral squamous cell carcinoma (53 papers, 2011 to 2026). "Also, elevated level of CSC marker CD44 is associated with expression of vascular adhesion protein VE-cadherin and VM presence in oral squamous cell carcinoma tissues." (PMID 38372877, 2024). "Furthermore, elevated expression of CD44 has been found to be associated with decreased survival in patients with oral squamous cell carcinoma 31-33." (PMID 38903932, 2024). "The authors concluded that CD44 (high)/CD24 (low) represents cancer stem-like cells in oral squamous cell carcinoma." (PMID 38138858, 2023). "p40 mediates up-regulation of keratin 6A, 14 and cancer stem cell marker CD44, which promotes abnormal differentiation of basal epithelial cells that lead to oral squamous cell carcinoma." (PMID 35741145, 2022). "One of the tissue markers scientists that are still interested in, due to peculiarities in its expression in different cancers (including oral squamous cell carcinoma and its precancerous conditions), is the glycoprotein CD44." (PMID 34830890, 2021). "There have been several studies on the role of Sol CD44 in the diagnosis of oral squamous cell carcinoma, but fewer on SolCD44 level changes in the saliva of epithelial dysplasia in the case of oral potentially malignant disorders, including leukoplakias." (PMID 34830890, 2021). "CD44-targeted NIR-PIT significantly suppressed tumor progression and prolonged survival in CD44-expressing syngeneic mouse models of oral squamous cell carcinoma." (PMID 34064074, 2021). "CDH11 and CD44 are over-expressed in oral squamous cell carcinoma (OSCC) and involved in OSCC metastasis." (PMID 33737587, 2021). "The study also suggested that miR-218-5p was downregulated in invasive front cells and that this miRNA negatively regulated oral squamous cell carcinoma invasiveness through targeting of the CD44-Rho kinase (ROCK) pathway." (PMID 34901284, 2021). "In oral squamous cell carcinoma, this method was used for the CD44, CD73, and mediator of DNA damage checkpoint protein 1 (MDC1 protein) evaluation." (PMID 33287350, 2020). "Notwithstanding, The patients outcome has also been influenced in oral squamous cells carcinoma, the CD44+ subpopulation was a independent factor of a poor prognosis." (PMID 23419168, 2013). "Expression of CD44, a transmembrane hyaluronan-binding glycoprotein, is variably considered to have prognostic significance for different cancers, including oral squamous cell carcinoma." (PMID 22242150, 2012). "Six probes targeting CD44 displayed significantly increased expression in the oral squamous cell carcinoma group relative to 95 other biological groups." (PMID 22242150, 2012). "Our previous work indicated higher CD44 expression in oral squamous cell carcinoma tissue compared to normal tissue counterparts." (PMID 22242150, 2012). "CSCs in oral squamous cell carcinomas show an increased expression of CD44, Oct4, Nanog, and Sox2, which may be utilized as candidate therapeutic targets." (PMID 37958336, 2023). "Furthermore, 5-mG2a-f (a defucosylated mouse IgG2a-type of clone C44Mab-5) for CD44 exerted antitumor effects in mouse xenograft models of oral squamous cell carcinomas." (PMID 34013368, 2021). "However, irregular or low expression of CD44 was related to poor prognoses in oral squamous cells carcinoma." (PMID 23419168, 2013). "In addition, CD44, a tumor stem cell marker for oral squamous cell carcinoma, showed high expression in radioresistant cells, indicating the possibility that SALL4 is associated with radioresistance in CD44( + )-OSCC cells." (PMID 38355684, 2024). "In contrast, inhibiting the expression of MMPs also inhibited the expression of CD44, for instance, DSPP/MMP20 gene silencing resulted in downregulation of CD44, a marker of oral squamous cell carcinoma (OSCC), and increased sensitivity to cisplatin." (PMID 38783892, 2024). "In conclusion, both CD44 and CD24 were expressed in oral squamous cell carcinoma." (PMID 37664387, 2023).
oral squamous cell carcinoma (continued). "In oral cavity squamous cell carcinoma, some studies indicated no prognostic value of CD44 expression." (PMID 34944493, 2021).
ovarian tumor (51 papers, 2006 to 2025). "Although a direct interaction of claudin-4 with CD44 has yet to be confirmed, CD44 expression has been found to be associated with claudin-4 expression in particularly aggressive ovarian tumor cells." (PMID 23521713, 2013). "The findings revealed that ovarian tumor cells expressed significant levels of CD44, particularly the v4/5 and v6 isoforms." (PMID 41440277, 2025). "FAK overexpression upregulates ALDH1 activity in platinum-resistant (and CD44 activity in taxane-resistant) ovarian tumors." (PMID 35820889, 2022). "Recurrent platinum-resistant ovarian tumors compared to primary tumors are enriched in the population of CD44+CD133+ALDH1A1+ OCSCs." (PMID 35269636, 2022). "The population of CD44+/E-cadherin-/CD34- inside ovarian tumors identify OCSCs cells with the ability to recapitulate the tumor and support neovascularization." (PMID 35269636, 2022). "Upon activation of CD44, which correlates with ovarian tumor cell invasive behavior, a signaling complex of CD44-IQGAP1-RAC1 formed to regulate actin activation, contributing to tumor cell migration." (PMID 34439095, 2021). "Tumor-associated macrophages (TAMs) are the main population of immune cells in ovarian tumor stroma, and CD44 and STAT3 both significantly contribute to tumor promoting properties of the ovarian TME." (PMID 33335857, 2020). "CD44 is a cell surface adhesion receptor and CD44+ cells have been reported to be present in primary and metastatic ovarian tumors as well as in cells of malignant ascites." (PMID 35582216, 2020). "More importantly in the context of this review, CD44+ stem-like cells have been shown to be markedly resistant to paclitaxel and platinum treatment, two standard front-line therapeutics against ovarian tumors." (PMID 33335857, 2020). "More importantly, CAFs also promote the CSC phenotype and chemoresistance development in ovarian tumor models and several studies have demonstrated that CD44 and STAT3 signaling pathways are involved in CAF-mediated therapy resistance." (PMID 33335857, 2020). "CD44-positive (CD44+) ovarian tumor cell subpopulations have been shown to express stem cell markers and are able to initiate tumorigenesis and promote disease recurrence by recapitulating the original tumor." (PMID 33335857, 2020). "Multiple markers, such as the Hoechst side population, CD133+, CD117 (c-KIT)+, ALDH1+ or CD44+ cells, have been described and used to identify CSCs from ovarian tumors." (PMID 31159852, 2019). "When CD44-siRNAs are delivered to ovarian tumours it down regulates CD44 resulting in prevention of HRG-mediated ovarian tumour cell growth and decreased migration." (PMID 29510526, 2018). "The published reports highlighted in this review provide further evidence that CD44 is one of the main players in ovarian tumor growth and metastasis." (PMID 26569327, 2015). "Flow cytometric analysis revealed lower frequencies of CD44+ cells in ascites and a higher frequency of EpCAM+ cells in miliary ovarian tumors." (PMID 25991672, 2015). "CD44+CD117+ cells isolated from human ovarian adenocarcinomas are a subpopulation with an ovarian tumor-initiating capacity, which can recapitulate original tumors from which they are derived when injected into mice." (PMID 23528891, 2013). "It remains to be demonstrated if simultaneous utilization of antibodies directed against mesothelin, CD44 and β-1 integrins will substantially inhibit binding of ovarian tumor cells to the mesothelium." (PMID 17067392, 2006). "Granted, other mechanisms such as CD44 interactions are also important while studying the metastasis of ovarian tumors." (PMID 17067392, 2006). "Finally, endothelial CD44 has been shown to be essential for wound healing and vascularization, as well as ovarian tumor angiogenesis in vivo." (PMID 33335857, 2020).
ovarian tumor (continued). "However, due to the large number of signaling networks modulated by CD44, it is important to define relevant CD44 molecular interaction partners that aid in the promotion of ovarian tumor resistance to front-line therapeutics in clinic." (PMID 33335857, 2020). "Additionally, higher ALDH and CD44 activities were detected in ascites-derived tumour cells than primary ovarian tumour cells." (PMID 32390009, 2020). "Recurrent ovarian tumors are enriched with cancer stem cell-like cells and stem cell mediators, such as CD44, CD133, NOTCH, Wnt, TGFbeta, ALDH1, thus supporting the hypothesis that cancer stem cells contribute to the disease recurrence." (PMID 29389895, 2018). "Recent work in the Mor and Santin laboratories has shown that high claudin-4 gene and protein expression are found in a population of CD44 positive (CD44+) ovarian tumor cells exhibiting stem cell-like properties as well as resistance to carboplatin and paclitaxel." (PMID 27724921, 2016). "CD44 is expressed in breast, prostate, colon, and ovarian tumors." (PMID 27655682, 2016). "Casagrande and colleagues have demonstrated the clostridium perfringens enterotoxin (CPE), recognizing a sequence in the second extracellular loop adjacent to the sequence recognized by DFYNP, is cytotoxic to the high claudin-4 expressing stem-like CD44+ ovarian tumor cells." (PMID 27724921, 2016). "Previous research has shown that human ovarian tumor cells can bind HA via membrane CD44." (PMID 26569327, 2015). "Low concentrations of metformin inhibited the secondary and the tertiary tumor sphere formation, decreased SKOV3 and primary ovarian tumor xenograft growth, enhanced the anticancer effect of cisplatin, and lowered the proportion of CD44+CD117+ CSCs in the xenograft tissue." (PMID 26718286, 2015). "Another study demonstrated that the glycosylation, but not the spliced variant content of CD44, affects the adhesive properties of ovarian tumor cells." (PMID 26569327, 2015). "However, in a previous report by our group, we reported more TSC ability to recapitulate tumor populations in CD44− than CD44+ cells isolated from OVCAR-5 ovarian tumor cell line." (PMID 22870217, 2012). "The ability of vitamin D to down‐regulate CD44 in vitro has been well described previously, notably in common cancers, where CD44 expression is elevated, and where 1,25(OH)2D has been reported to decrease the stem cell‐like characteristics of cancers such as ovarian tumours." (PMID 39739404, 2025). "Moreover, transfection of CD44+⁄CD117+ cells enriched from human primary ovarian tumor tissues with miR-199a, significantly decreased CD44 mRNA and protein expression while significantly affecting cell cycle regulation, suppressing proliferation, and increasing chemosensitivity of ovarian CICs." (PMID 26569327, 2015). "Through FAK inhibition, APG-2449 sensitizes ovarian xenograft tumors to paclitaxel by reducing CD44+ and aldehyde dehydrogenase 1-positive (ALDH1+) cancer stem cell populations, including ovarian tumors insensitive to carboplatin." (PMID 35820889, 2022). "Some researchers have proposed ovarian tumor stem cell-specific biomarkers such as CA24, CD44, CD133, and SSEA, and others have proposed the unique peritoneal microbial profile of OC patients." (PMID 36185223, 2022). "Finally, CD44-EpCAM (Epithelial Cell Adhesion Molecule) aptamer is a double-stranded RNA adaptor which acts blocking both, CD44 and EpCAM, simultaneously reducing tumor progression and promoting apoptosis, both in vitro and in vivo xenograft models of ovarian tumor cells (OVCAR8)." (PMID 35785191, 2022). "CD44+/CD117+ cells isolated from human ovarian tumors express high levels of TG2, and in vitro treatment of IGROV1 cells with TGF-β enhanced spheroid formation in culture and increased the number of CD44+/CD117+ cells." (PMID 36437919, 2022). "Previous report showed that MSCs (CD44+, CD73+, CD90+) represent around 6% of the full cell population in human ovarian tumor ascites." (PMID 29455640, 2018).
ovarian tumor (continued). "We evaluated sections from 3 poorly differentiated malignant ovarian tumors and found occasional cells (< 1%) that were co-stained with ALDH1 and CD44." (PMID 21176222, 2010). "Moreover, sensitivity to cisplatin was also improved in a mouse ovarian tumor model using anti-SPP1 and anti-CD44 antibodies." (PMID 38515213, 2024). "Histopathological examination showed that after magnetic-induced heating of the CD44-shRNA/DDP magnetic nanoliposomes, the ovarian tumor tissue presented a large red map-like necrotic focus, the tumor cells displayed coagulative necrosis, and the nucleus disintegrated and disappeared." (PMID 35402279, 2022). "Furthermore, we observed upregulation of the mitochondrial gatekeeping enzyme, PDK4, in not only ascites-derived cancer cells relative to primary ovarian tumour cells but also in tumourspheres and the ALDH+CD44+ subset." (PMID 32390009, 2020). "Therefore, CD44 and STAT3 crosstalk deserves further investigation to identify promising novel strategies to sensitize ovarian tumors to treatment and prevent disease relapse." (PMID 33335857, 2020). "Of importance, the CD44+ population has significantly higher levels of claudin-4 compared to CD44 negative (CD44−) ovarian tumor cells isolated from the same tumor." (PMID 27724921, 2016). "In summary, this is a preliminary study that is the first proof for demonstrating the SKOV3 CD117+CD44+CSC vaccine targets effectively CSCs and inhibits ovarian tumor growth in xenografted nude mice by eliciting effective immune resonses against SKOV3 CD117+CD44+ CSCs." (PMID 26497895, 2015). "Furthermore, several cell surface markers, including CD44, CD117, CD133, CD24 and aldehyde dehydrogenase-1 A1 (ALDH1 or ALDH1A1), or a combination of these markers, define ovarian CSC/TIC populations in ovarian tumors." (PMID 23528891, 2013). "Furthermore, several markers able to define a CIC population in primary ovarian tumors have been discovered, for example, CD44+CD117+, CD133+, CD24+ and CD44+/MyD88+." (PMID 21541038, 2011). "Therefore, it is reasonable to postulate that CD44 and STAT3 not only mediate CAF-driven ovarian tumor stemness and chemoresistance within tumor cells, but also cooperate within CAFs themselves to support their cancer-promoting phenotype, which requires further investigation." (PMID 33335857, 2020). "Collectively, these observations indicate that CD44 and STAT3 molecular cooperation deserves further attention and may be a promising clinical target to develop more effective therapeutics for the treatment of ovarian tumors." (PMID 33335857, 2020). "CD44 has been shown to be a useful tumor marker for disease progression and metastasis in certain types of cancers, and our laboratory, as well as others, has shown that CD44 is not usually expressed in the normal ovary although it is expressed in 40-60% of primary ovarian tumors." (PMID 26299618, 2015).